BAX (BCL2 associated X, apoptosis regulator)
Diseases named in the same sentence as BAX in open-access papers (continued):
Sharing a sentence is not in itself a finding about the gene and the disease.
infection (continued). "BAK, BAX, FADD, IKKα and all showed decreases in abundance in Makona or Ecran infected A549 and NPro cells compared with mock infection." (PMID 28240256, 2017). "We showed that transient expression of each of these seven VmEPs significantly suppressed BAX-induced PCD in N. benthamiana, five genes of which were up-regulated during infection." (PMID 26284095, 2015). "Several apoptosis-related molecules such as caspase 3, caspase 8, caspase 9, and BAX appeared to be induced under conditions of reduced IFIT3, and the expression of these molecules was further enhanced by DV infection." (PMID 24223959, 2013). "The fact that SFTSV induces BAK/BAX-dependent release of mitochondrial DNA, as previously documented, corroborates the current finding that SFTSV infection directly triggers mitochondrial dysfunction and pyroptosis, leading to extracellular release of mtDNA in HUVECs." (PMID 40366175, 2025). "During infection, STING activates IRF3 which interacts with BAX." (PMID 38459007, 2024). "Nonetheless, we also observed that the ratio between the anti-apoptotic BCL2 and pro-apoptotic BAX genes was significantly increased in SARS-CoV-2 infected iPSC-MNs, suggesting that programmed cell death is somehow prevented following infection in these neuronal cells." (PMID 38116398, 2023). "On the other hand, proapoptotic proteins BAD and BAX have not shown changes in their protein expression after infection with sh-RUNX2." (PMID 36510562, 2022). "BAX/BAK-interacting partners BID, BIM, and PUMA are individually dispensable but contribute together, consistent with the potential diversity of BAX and BAK activators as infection progresses." (PMID 34578288, 2021). "These single-mutant cells all exhibited a similar pattern of infection with either virus comparable to WT settings, demonstrating that, individually, BID, BIM, PUMA, or BOK are dispensable for suppression of ∆vMIA/vIBO-driven, BAX/BAK-mediated PCD." (PMID 34578288, 2021). "Although Huh7 cells induced cell death at 4 days post-infection with JEV, BAX/BAKDKO cells exhibited a complete resistant to mitochondria mediated apoptosis, suggesting that cells infected with JEV induce mitochondria-mediated apoptosis at 4 days post-infection." (PMID 30261081, 2018). "Together, these data suggest that while ΔflaA L. pneumophila can induce BAX/BAK-mediated apoptosis in late stage infections, it is not critical for bacterial replication." (PMID 28261564, 2017). "However, Ad-HRD1 infection suppressed the PA-induced expression of cleaved PARP, cleaved caspase-3, and BAX." (PMID 29233968, 2017). "Our temporal analyses revealed that at later infection stages (36–48 hours post-infection [hpi]), SARS-CoV-2 exploits TGF-β-induced lysosomal membrane permeabilization (LMP) and apoptosis for viral release—processes effectively inhibited by SB431542 through suppression of GADD45b and BAX expression." (PMID 40879372, 2025). "Given the recognized crucial functions of BID, BIM, PUMA, and BOK in activating BAX/BAK-dependent cell death, we assessed viability and viral titer in WT compared to Bid−/−Bim−/−Puma−/− as well as Bid−/−, Bim−/−, Puma−/−, and Bok−/− BMDM during infection with K!81 or ∆M38.5/M41.1 viruses." (PMID 34578288, 2021).
infection (continued). "Intrinsic BAX/BAK-dependent apoptosis or caspase-9 cleavage has been reported following H5N1 and seasonal H1N1 infection of human primary type I-like alveolar epithelial cells, as well as PR8 infection of A549 cells, primary murine tracheal cells and H7N9-infection of human blood-derived monocytes." (PMID 32260457, 2020). "However, BAX/BAKDKO cells also exhibited cell death at 5 and 6 days post-infection." (PMID 30261081, 2018). "By contrast, the protein levels of BCL-2, BCl-XL, BAX, BAK, BIM, and BID, as well as mRNA levels of BAX, were not affected by SAMHD1 expression or HIV-1NL4-3 infection of THP-1 cell lines." (PMID 40434097, 2025). "During the early infection (24 hpi), WSSV did not change the expression of pro-apoptosis factor BAX and we observed a slight increase in the expression of anti-apoptosis factor BI-1 in crayfish." (PMID 37855526, 2023). "The following steps occurred: HtrA2/Omi, together with BAX and BAK, restricts K181 infection even in the presence of vMIA and vIBO without influencing cell viability." (PMID 34578288, 2021). "Whereas MG132 and arsenic trioxide failed to increase BAX 335-mediated FIX expression in HepG2 cells (data not shown), pretreatment of cells with HU boosted infection over a concentration range of 1–10 mM." (PMID 32280725, 2020). "Deletion of both BAX and BAK resulted in a 15–20% decrease in the rate of cell death compared to WT, or deletion of BAK alone, between 30 and 40 h post infection, but not during the initial killing phase (10–25 h)." (PMID 28261564, 2017). "Up-regulation of apoptotic genes like BAX, BAK1 in H5N1 (WB-NIV2664) but not in IBCDC-RG7 infection could be a part of cytokine mediated response." (PMID 20828378, 2010).
adenocarcinoma (7 papers, 2012 to 2025). A common cancer characterized by the presence of malignant glandular cells. "We examined the expression of several proteins involved in proliferation (PCNA), apoptosis (PARP, caspase-3, BAX, BCL-2, and BCL-XL and mammary carcinogenesis (ERα and HER2) in carefully selected representative sentinel adenocarcinomas from each diet group." (PMID 24465421, 2014). "On the other hand, most of examined BCL-2 family members involved in the intrinsic death pathway were found over-expressed in almost all adenocarcinoma cell lines utilized: BCL-2 protein in RKO cell line being the most upregulated, other overexpressed factors of this family are BAK and BAX." (PMID 27520705, 2016).
neurodegenerative disease (7 papers, 2015 to 2025). A disorder of the central nervous system characterized by gradual and progressive loss of neural tissue and neurologic function. "Previous studies have demonstrated that dysregulated metabolism of DNA epigenetic modifications leads to the regulation of neuronal apoptosis-related gene expression, including BAX and Bcl-2, in the pathogenesis of neurodegenerative disease." (PMID 40386213, 2025). "Although considerable research has focused on enhancing the apoptotic function of BAX for several decades, inhibition of its functionality remains relatively underexplored, despite intensive BAX activation occurring in various neurodegenerative diseases." (PMID 41449208, 2025). "Importantly the imminent development of specific small-molecule inhibitors of BAX will provide the initial tools needed to parse mechanistic details of the coordinate regulation of apoptosis, necroptosis, and other forms of cell death in the pathology of neurodegenerative disease." (PMID 33162554, 2021).
neurological disorders (6 papers, 2020 to 2025). "Our findings revealed a significant reduction in BCL2 gene expression and protein levels, and a notable increase in BAX levels, indicating an imbalance that likely contributed to the enhanced neuronal cell death associated with this neurological disorder." (PMID 41523603, 2025). "In CR, 52 AD-related target proteins were validated to bind with 25 active ingredients, including ACHE, APP, BCHE, BCL2, BAX, CASP3, and CASP7, and are implicated in cell apoptosis and vascular and nervous system diseases." (PMID 32802132, 2020). "On the other side, cotreatment with WSLE and WSLE NE revealed a signification downregulation of APP, GFAP, vimentin, TGF-β, Smad2, and BAX target genes which coincided with previous studies which highlighted the neuroprotective effect of WSLE in a variety of neurological disorders." (PMID 38630361, 2024).
cardiac disease (4 papers, 2011 to 2025). "These previous studies and our results suggest that the protein levels of apoptotic-related factors such as BCL2 and BAX may play a vital role in the initiation and development of cardiac disease in DRM." (PMID 21541347, 2011). "Our results show that cytosolic homo/heterodimerization of BNIP3 and interaction with mitochondria via mitochondrial BAX does not affect MIM potential and cell viability, unlike what was assumed to occur in cardiac disease." (PMID 28333095, 2017).
colon (3 papers, 2019 to 2025). "In contrast, colon carcinogenesis is linked with reductions in cyclin-dependent kinase (CDK) inhibitors (p21 and p27), BCL2-associated X protein (BAX), cytochrome C (Cyto-C), and caspase-3 (Casp-3) proteins." (PMID 35326689, 2022).
hematological malignancies (3 papers, 2022 to 2025). "When both BCL-XL and BCL-2 proteins are expressed at similar levels, as evidenced mainly in hematological malignancies, then both proteins can regulate BAX activation." (PMID 35256598, 2022). "Here, we find that apoptosis resistance in a diverse panel of solid and hematological malignancies is mediated by both overexpression of BCL-XL and an unprimed apoptotic state, limiting direct and indirect activation mechanisms of pro-apoptotic BAX." (PMID 35256598, 2022). "Our findings provide preclinical proof-of-concept for the combination treatment of a new orally bioavailable BAX activator, BTSA1.2, and Navitoclax, which may provide a broad therapeutic effect in solid tumors and hematological malignancies." (PMID 35256598, 2022).
bacterial infection (2 papers, 2017 to 2025). "Cellular stresses, including bacterial infections, can promote activation of the pro-apoptotic BH3-only proteins that either directly, or indirectly, induce BAX/BAK-mediated apoptosis." (PMID 28261564, 2017).
kidney disease (2 papers, 2020 to 2023). "These proteins are inhibited by pro-survival Bcl-2 proteins and many studies have demonstrated that BAX and BAK proteins participate in apoptotic/necrotic process in kidney disease and the silencing of their functions could prevent apoptosis and the subsequent fibrogenic signaling." (PMID 37760081, 2023).
blood cancers (1 paper, 2023). "In this study, we have identified factors (loss of BAX; gain of BCL-XL and/or A1) that confer resistance to the new class of BH3-mimetics targeting MCL-1, drugs which are currently being evaluated in clinical trials for diverse blood cancers." (PMID 36755070, 2023).
hematological cancers (1 paper, 2020). "Of note, BIM is deleted in 17% of MCL, while BAX mutations occur in 20% of hematologic cancers such as CLL, FL, MCL and NHL." (PMID 32131385, 2020). "Somatic inactivation of BAX (and BAK) has been reported in both solid and hematological cancers." (PMID 32131385, 2020).
inflammation (1 paper, 2023). Aberrant reaction of the microcirculation characterized by movement of fluid and leukocytes from the blood into extravascular tissues. "The histology and TNF-alpha and BAX immunostaining evaluation in animals treated with FA verify the CRS type 3 development, characterized by heart inflammation and cell death induction." (PMID 37627587, 2023).
BAX also shares sentences with these, for which no sentence is quoted: multiple myeloma (6 papers); cardiovascular disease (4); lung (4); mesothelioma (4); acute leukemia (3); autoimmune disorders (3); clear cell renal carcinoma (3); small cell lung carcinoma (3); adenovirus infection (2); Arthritis (2); bipolar disorder (2); cerebral infarction (2); dry eye (2); endothelial dysfunction (2); follicular lymphoma (2); hemangioma (2); HIV-1 infection (2); idiopathic pulmonary fibrosis (2); immune disorders (2); pancreatic adenocarcinoma (2); prostate adenocarcinoma (2); systemic lupus erythematosus (2); acute myocardial infarction (1); adrenocortical cancer (1); Allergy (1); amyloid (1); ankylosing spondylitis (1); arteriosclerosis (1); Ascites (1); asthenozoospermia (1).
A further 98 diseases each share a sentence with BAX in 1 paper.